TRPM2 (transient receptor potential cation channel subfamily M member 2)
Diseases named in the same sentence as TRPM2 in open-access papers (continued):
Sharing a sentence is not in itself a finding about the gene and the disease.
breast adenocarcinoma (6 papers, 2015 to 2023). "We show here that inhibition of TRPM2 function causes decreased proliferation and increased levels of DNA damage in breast adenocarcinoma cells, with minimal effects in normal breast cells." (PMID 25760245, 2015). "We previously demonstrated that TRPM2 inhibition or RNAi silencing caused increased levels of DNA damage in breast adenocarcinoma cells." (PMID 26178079, 2015). "Thus, the results of these studies indicated that inhibition of TRPM2 caused increased levels of cell death in the MDA-MB-231 breast adenocarcinoma cells after chemotherapeutic treatments." (PMID 26178079, 2015). "TRPM2 was situated within the nucleus of breast adenocarcinoma but not limited to that place; about 40–45% of TRPM2 was in the nucleus while the remaining part was in subcellular sections involving the cytoplasm." (PMID 37337283, 2023). "Taken together, the results show that the pharmacologic inhibition or RNAi silencing of TRPM2 led to increased levels DNA damage in human breast adenocarcinoma cells." (PMID 25760245, 2015). "Further, we expand upon these findings by identifying a novel protective effect of TRPM2 in breast adenocarcinoma cells." (PMID 25760245, 2015). "As we previously demonstrated that inhibition of TRPM2 led to decreased proliferation in breast adenocarcinoma cells, we next investigated the ability of TRPM2 inhibition to induce cell death." (PMID 26178079, 2015). "Our studies also provided important mechanistic and therapeutic insight into the cell death pathways induced by TRPM2 inhibition after chemotherapeutic treatments in breast adenocarcinoma cells." (PMID 26178079, 2015). "We successfully decreased TRPM2 protein levels in the MDA-MB-231 breast adenocarcinoma cells by RNAi silencing." (PMID 26178079, 2015). "We next determined the effect of TRPM2 pharmacologic inhibition and RNAi silencing on breast adenocarcinoma cell proliferation." (PMID 25760245, 2015). "Taken together, the results of the pharmacologic inhibition of TRPM2 and RNAi silencing of TRPM2 indicate that TRPM2 has a role in facilitating the proliferation of human breast adenocarcinoma cells." (PMID 25760245, 2015). "Quantification of protein levels by densitometry indicated that ~40–45% of the TRPM2 protein present in human breast adenocarcinoma cells was localized to the nucleus." (PMID 25760245, 2015). "While we previously demonstrated a novel role for TRPM2 in breast adenocarcinoma cells, where it was shown to mediate DNA damage levels and cell proliferation, we expand upon these findings by reporting increased cell death due to inhibition of TRPM2." (PMID 26178079, 2015). "To investigate a possible nuclear role of TRPM2 in human breast adenocarcinoma cells, we determined the effect of TRPM2 pharmacologic inhibition and TRPM2 RNAi silencing on the levels of DNA damage in MCF-7 and MDA-MB-231 cells." (PMID 25760245, 2015). "In two lines of metastatic breast adenocarcinoma cells, greater levels of TRPM2 were observed in the MDA-MB-231 cell line as compared to the MCF-7 cell line." (PMID 25760245, 2015). "TRPM2 inhibition led to dose-dependent increases in MDA-MB-231 breast adenocarcinoma cell death after treatment with doxorubicin or the DNA-methylating agent, N-methyl-N'-nitro-N-nitrosoguanidine." (PMID 26178079, 2015). "Taken together, our results provide significant evidence that TRPM2 inhibition is a potential strategy to induce triple-negative and estrogen receptor-positive breast adenocarcinoma cell death via alternative cell death pathways." (PMID 26178079, 2015). "Our study therefore provides compelling evidence that TRPM2 has a unique role in breast adenocarcinoma cells." (PMID 25760245, 2015). "Our preliminary findings indicate that TRPM2 inhibition is expected to induce alternative cell death pathways in breast adenocarcinoma cells." (PMID 26178079, 2015).
breast adenocarcinoma (continued). "The lack of a primary role for apoptosis, autophagy or PAR-mediated caspase-independent cell death in breast adenocarcinoma cells after TRPM2 inhibition and chemotherapeutic treatments suggests that necrosis is the primary cell death pathway induced." (PMID 26178079, 2015). "Further studies will be necessary to determine if TRPM2 mediates significant levels of calcium influx into the cytoplasm or nuclei of breast adenocarcinoma cells." (PMID 25760245, 2015). "To analyze TRPM2 function, we utilized the Fluo-4 NW calcium assay to quantify calcium influx into breast adenocarcinoma cells after stimulation by hydrogen peroxide, as this assay was previously utilized to measure calcium influx due to TRPM2 channels." (PMID 25760245, 2015). "This indicates that TRPM2 has a protective role in these lines of human breast adenocarcinoma cells, where it somehow minimizes damage to genomic DNA." (PMID 25760245, 2015). "In breast adenocarcinoma cells after 48 h of RNAi silencing, TRPM2 levels were decreased more than 75% in the MCF-7 cell line and ~80% in the MDA-MB-231 cell line as compared to control levels." (PMID 25760245, 2015). "TRPM2 displayed a defensive action in human breast adenocarcinoma cell lines to minimize DNA destruction, where cell proliferation declined and DNA damage climbed up significantly through pharmacological cessation of TRPM2 including 2-APB or TRPM2 mRNA silencing." (PMID 37337283, 2023). "However, in MCF-7 and MDA-MB-231 human breast adenocarcinoma cells, TRPM2 was present in the nuclear fractions of these cells." (PMID 25760245, 2015). "Increased cell death was observed in TN and ER+ breast adenocarcinoma cells after TRPM2 inhibition." (PMID 26178079, 2015). "Thus, via the use of 2-APB, we analyzed the ability of TRPM2 channels to promote calcium influx in breast adenocarcinoma cells after oxidative stress." (PMID 25760245, 2015). "However, in both MCF-7 and MDA-MB-231 breast adenocarcinoma cells, RNAi silencing of TRPM2 led to increased amounts of cells with comets as compared to cells transfected with negative control scrambled siRNA oligos." (PMID 25760245, 2015). "In summary, we discovered a novel role for TRPM2 in breast adenocarcinoma cells." (PMID 25760245, 2015). "Because of the possibility that TRPM2 may have a novel role in human breast adenocarcinoma cells, our next objective was to determine its intracellular localization." (PMID 25760245, 2015). "Thus, our study provides the preliminary results necessary to further study the ability of TRPM2 pharmacologic inhibition to prevent the survival, proliferation, and/or metastasis of breast adenocarcinoma cells." (PMID 25760245, 2015). "Since this ability is a unique feature of TRPM2 channels, it may prove to be significant in maintaining the survival, proliferation, or limiting DNA damage in breast adenocarcinoma cells." (PMID 25760245, 2015). "Thus, more studies are required in order to determine the primary cell death pathway(s) involved in breast adenocarcinoma cells after TRPM2 inhibition." (PMID 26178079, 2015). "Similar results regarding TRPM2, another member of the TRP family, have been obtained in prostate cancerous cell lines and in breast adenocarcinomas." (PMID 31013784, 2019). "We also used an additional TRPM2 inhibitor, 2-aminoethoxydiphenyl borate (2-APB), to further demonstrate the effects of TRPM2 inhibition on cell death in the MDA-MB-231 breast adenocarcinoma cells." (PMID 26178079, 2015). "Although TRPM2 channels are nearly ubiquitously expressed, we first analyzed the presence of TRPM2 channels in two lines of noncancerous human mammary epithelial cells and two lines of human breast adenocarcinoma cells by western blotting." (PMID 25760245, 2015). "However, we demonstrated here that TRPM2 was present in the nuclei of MCF-7 and MDA-MB-231 human breast adenocarcinoma cells, and its pharmacologic inhibition or RNAi silencing caused decreased cell proliferation." (PMID 25760245, 2015).
breast adenocarcinoma (continued). "However, TRPM2 RNAi silencing also led to increased MCF-7 breast adenocarcinoma cell death after tamoxifen treatment, yet not in non-cancerous human mammary epithelial cells." (PMID 26178079, 2015). "Due to this regulation of TRPM2 channels by PAR, along with the ability of activated TRPM2 channels to facilitate cell death in non-cancerous cells, the lack of caspase-independent cell death after TRPM2 inhibition in breast adenocarcinoma cells was unexpected." (PMID 26178079, 2015). "Therefore, the studies suggest that apoptosis and autophagy are not the primary pathways of cell death induced by TRPM2 inhibition in breast adenocarcinoma cells after chemotherapy." (PMID 26178079, 2015).
glioma (5 papers, 2020 to 2023). A benign or malignant brain and spinal cord tumor that arises from glial cells (astrocytes, oligodendrocytes, ependymal cells). "Both TRPM2 and TRPM3 have demonstrated protective roles in glioma; however, TRPM2 has been more thoroughly studied." (PMID 36768856, 2023). "Four TRP melastatin subfamily members, TRPM2, TRPM3, TRPM7, and TRPM8, have been implicated in glioma cell growth, proliferation and migration." (PMID 33928077, 2021). "Several TRP channels have been studied as potential biological markers of glioma progression and prognosis, including TRPC1, TRPC6, TRPM2, TRPM3, TRPM7, TRPM8, TRPV1/2." (PMID 36768856, 2023). "There is a growing consensus that TRPV1, TRPV2, TRPM2, TRPM3, and TRML1 exert anti-tumorigenic properties in glioma, while TRPC1, TRPC6, TRPM7, TRPM8, and TRPML2 promote glioma growth and proliferation." (PMID 36768856, 2023). "Previous reports indicated that TRPM2, ICOSLG are potential oncogenes in glioma." (PMID 35521558, 2022). "Among them, TRPM2 and TRPM3 would exert anti-tumorigenic effects, while TRPM7 and TRPM8 may contribute to glioma malignancy." (PMID 33928077, 2021). "Like TRPM2, TRPM3 may show a protective role in glioma probably via the miR-204 regulation, but its function needs further studies." (PMID 33928077, 2021).
head and neck cancer (5 papers, 2019 to 2023). A primary or metastatic malignant neoplasm affecting the head and neck. "TRPM2 was previously found to contribute to irreversible loss of salivary gland function following irradiation, which is a severe side effect of radiotherapy for head and neck cancers." (PMID 30483886, 2019). "The outcome is that TRPM2 has a role in the survival and movement of SCC cancer cells along with in head and neck cancers, it can be a possible therapeutic object." (PMID 37337283, 2023).
lupus (5 papers, 2018 to 2025). "Our data demonstrate that CD38 promotes pristane-induced chronic inflammation and increases susceptibility to experimental lupus by an apoptosis-driven and Transient Receptor Potential Melastatin 2 (TRPM2)-dependent mechanism." (PMID 30257456, 2018). "Using the pristane lupus model, we have demonstrated the crucial role of CD38 in promoting aberrant inflammation and lupus-like autoimmunity via an apoptosis-driven mechanism, which requires TRPM2 expression." (PMID 34504495, 2021). "In a previous study using the pristane lupus model, we demonstrated the crucial role for CD38 in promoting aberrant inflammation and lupus-like autoimmunity via an apoptosis-driven mechanism, which requires TRPM2 expression." (PMID 34504495, 2021). "Hence, our data suggest that CD38 deficiency protects mice from pristane-induced lupus in a TRPM2-dependent manner by reducing the number of intraperitoneal apoptotic cells, which are the primary source of autoantigens in this murine model of SLE." (PMID 29463868, 2018). "In summary, CD38 enhances the development of pristane-induced lupus by regulating the cell death of Ly6Chi monocytes and Ly6Clo monocytes/macrophages in a TRPM2-dependent and ART2-independent manner that worsens the early inflammatory response in the peritoneum." (PMID 29463868, 2018).
myocardial infarction (5 papers, 2015 to 2025). Gross necrosis of the myocardium, as a result of interruption of the blood supply to the area, as in coronary thrombosis. "UA promoted cardiomyocyte injury through activation of the NLRP3 inflammasome and ROS/transient receptor potential melastatin 2 (TRPM2) channel/Ca2+ pathway in a myocardial infarction animal model." (PMID 38474414, 2024). "Consistently, myocardial infarction after I/R, but not ischemia alone, and post-ischemic cardiac contractile dysfunction were strongly reduced in the TRPM2-KO mice." (PMID 26300888, 2015). "The in vivo gating dynamics of atrial TRPM2 under ISO—including possible ROS/ADPr microdomains—remain undefined, and it is unknown whether these atrial findings generalize to pressure overload or myocardial infarction." (PMID 41511308, 2025).
ovarian carcinoma (5 papers, 2023 to 2026). A malignant neoplasm originating from the surface ovarian epithelium. "Among the 10 candidate DEERGs, a significant association between the expression of TRPM2 and the survival of ovarian cancer patients in the TCGA database was discovered." (PMID 37762313, 2023). "To clarify the underlying mechanisms of TRPM2 affecting the survival of ovarian cancer patients, we conducted a GSEA algorithm with TCGA-OV and GSE17260 databases after the calculation of fold change of genes according to TRPM2 expression." (PMID 37608401, 2023). "The results of bioinformatics research revealed a significant association between decreased expression of TRPM2 and improved prognosis in ovarian cancer patients." (PMID 37762313, 2023). "In addition, in the OV cohort, TRPM2 was also associated with several chemokines and chemokine receptors that have been shown to promote ovarian cancer progression and metastasis, such as CXCL11-CXCR3 and CXCL12-CXCR4 chemokine axes." (PMID 37569287, 2023). "The results indicated that TRPM2 expression was significantly related to the prognosis of ovarian cancer patients and may act as a risk factor in OC." (PMID 37608401, 2023). "For example, TrpV4, TrpC7, and several TrpM family members (TrpM2, TrpM4, TrpM8) are upregulated in ovarian cancer, where their expression negatively correlates with patient prognosis." (PMID 41557739, 2026). "In this study, we observed abnormal expression of TRPM2 expression in most tumors and survival correlation in some tumors containing ovarian cancer." (PMID 37608401, 2023). "Our results showed that TRPM2 was upregulated in most tumors containing ovarian cancer, and increased TRPM2 expression was correlated with poor OS and PFI in patients with OC." (PMID 37608401, 2023). "Our study demonstrated that TRPM2 is a poor prognostic prediction factor in ovarian cancer and is correlated to the immune microenvironment and pyroptosis." (PMID 37608401, 2023). "Compared to the sh-NC group, we observed that knockdown of TRPM2 promoted ovarian cancer cell apoptosis." (PMID 37569287, 2023). "Flow cytometry analysis showed that TRPM2 plays a crucial role in the cell cycle of ovarian cancer cells and inhibits apoptosis." (PMID 37762313, 2023). "We examined the relationship between TRPM2 and pyroptosis in ovarian cancer by real-time quantitative PCR." (PMID 37608401, 2023). "Together, these results indicated that TRPM2 played an essential role in regulating ovarian cancer immune infiltrating cells." (PMID 37608401, 2023). "For instance, TRPM2 was significantly upregulated in ovarian cancer cells compared to normal cells, and TRPM2 promoted intracellular ROS and the invasion and migration of ovarian cancer cells." (PMID 37762313, 2023). "Ovarian cancer (OV) specimens were enrolled to test the expression of TRPM2 by immunohistochemistry and RT-qPCR." (PMID 37569287, 2023). "Our research provided more information for a better understanding of the significance of TRPM2 in various cancers, highlighting the potential of TRPM2 as a therapeutic target for ovarian cancer treatment." (PMID 37569287, 2023). "This suggested that the TRPM2 may be used as a marker to predict the effect of immunotherapy, particularly for patients with ovarian cancer." (PMID 37569287, 2023). "We created a 10-ERG risk classifier that displays a powerful capability of survival evaluation for EOC cases, and TRPM2 could be a potential therapeutic target of ovarian cancer cells." (PMID 37762313, 2023). "To date, few studies have investigated the role of TRPM2 in ovarian cancer." (PMID 37762313, 2023). "The downregulation of TRPM2 levels resulted in an elevation in intracellular reactive oxygen species (ROS) levels, indicating that TRPM2 may have enhanced ovarian cancer cell activity by inhibiting ROS." (PMID 37762313, 2023).
ovarian carcinoma (continued). "Our study demonstrated that TRPM2 was a hazard factor for OC patients which might result from immune regulation, and could be a potential prognosis-predict biomarker for ovarian cancer patients." (PMID 37608401, 2023). "Immunohistochemistry results in The Human Protein Atlas suggested a high expression of TRPM2 in ovarian cancer tissues compared with normal tissues, which was also confirmed by our clinical samples, showing that TRPM2 is highly expressed in ovarian cancer patients." (PMID 37608401, 2023). "Furthermore, further research and exploration are needed to investigate the exact role of TRPM2 in the pathogenesis of ovarian cancer and its potential therapeutic value." (PMID 37762313, 2023). "Therefore, we claim that TRPM2 has a promoting effect on the development and metastasis of ovarian cancer and could be a potential therapeutic target." (PMID 37762313, 2023). "In addition, TRPM2 could be a potential therapeutic target of ovarian cancer cells." (PMID 37762313, 2023). "Not only that, but the RT-qPCR results from clinical specimens also validated the upregulated TRPM2 expression and positive correlation between the expression level of TRPM2 and M2 macrophage marker CD206 in ovarian cancer." (PMID 37569287, 2023).
type 2 diabetes mellitus (5 papers, 2015 to 2024). A type of diabetes mellitus that is characterized by insulin resistance or desensitization and increased blood glucose levels. "The novel β-cell specific GHSR-cAMP/TRPM2 signaling provides a potential therapeutic target for the treatment of type 2 diabetes." (PMID 26370322, 2015). "This indicates that TRPM2 may play a critical role in the pathogenesis of (type 1 diabetes) T1D and (type 2 diabetes) T2D by mediating oxidative stress-induced pancreatic β-cell death." (PMID 39007141, 2024). "Hence, developing methods to specifically intervene the GHSR-cAMP/TRPM2 cascade in β-cells may provide a potential therapeutic tool to treat patients with type 2 diabetes." (PMID 26370322, 2015).
ulcerative colitis (5 papers, 2014 to 2025). An inflammatory bowel disease involving the mucosal surface of the large intestine and rectum. "In a dextran sodium sulfate (DSS)-induced ulcerative colitis model, TRPM2 KO mice showed reduced CXCL2 expression, decreased neutrophil infiltration, and attenuated colonic inflammation." (PMID 39007141, 2024). "The TRPM2 gene was biologically plausible as a candidate gene because TRPM2 has been shown to increase tissue damage at sites of inflammation in a mouse model of ulcerative colitis." (PMID 27919223, 2016). "In a mouse model of ulcerative colitis, the over-abundance of neutrophil invasion into tissue mediated by TRPM2 expression, led to increased colonocyte death." (PMID 24892408, 2014).
acute kidney injury (4 papers, 2021 to 2025). Sudden and sustained deterioration of the kidney function characterized by decreased glomerular filtration rate, increased serum creatinine or oliguria. "TRPM2 suppression effectively improved ischemia-reperfusion associated acute kidney injury by inhibiting inflammation." (PMID 34845114, 2021). "Moreover, TRPM2 mediates acute kidney injury via a mechanism that involves the activation of Rac Family Small GTPase 1 (RAC1), oxidative stress, and mitochondrial apoptotic pathways." (PMID 37275121, 2023).